Y_RNA (Y RNA )
Gene: Miscellaneous RNA gene on chromosome 7 (23,491,792 to 23,491,893, reverse strand). Ensembl gene ENSG00000200847.
Homologues: Orthologues: chimpanzee Y_RNA (100% identical), macaque Y_RNA (95% identical). Paralogues in human: RNY3 (91% identical), Y_RNA (91% identical), RNY3P1 (90% identical), Y_RNA (90% identical), Y_RNA (89% identical), Y_RNA (88% identical), Y_RNA (87% identical), RNY3P11 (86% identical), Y_RNA (86% identical), RNY3P14 (85% identical), RNY3P16 (85% identical), Y_RNA (85% identical), and 96 more.